CAT (catalase)
Diseases named in the same sentence as CAT in open-access papers (continued):
Sharing a sentence is not in itself a finding about the gene and the disease.
age (3 papers, 2011 to 2023). A temporal measurement of the time period elapsed since an identifiable point in the life cycle of an organism. "We have previously shown that transgenic expression of the antioxidant enzyme catalase targeted to the mitochondria (mCAT) in mice reduces ROS, attenuates age‐related disease, and increases lifespan." (PMID 27061426, 2016).
asthenozoospermia (3 papers, 2007 to 2022). "The aim of the present study was to assess seminal plasma levels of TAC and free 8-Isoprostane and activities of catalase and SOD in men with asthenozoospermia, asthenoteratozoospermia and oligoasthenoteratozoospermia compared to normozoospermic males." (PMID 17540046, 2007). "The asthenospermia mouse model showed high activity of MDA and proinflammatory factors (TNF-α, IL-6), as well as low expression of antioxidants (SOD, GSH-Px, CAT) in the testis and epididymis, but this situation could be significantly ameliorated after being treated with CNP." (PMID 36142279, 2022).
astrocytoma (3 papers, 2009 to 2024). "Moreover, pretreatment with catalase abrogates perturbance of ΔΨm, JNK activation and rescues astrocytoma cells from triterpene-induced damage, indicating that ROS is the up-regulator of JNK activation during triterpene dialcohols-induced apoptosis." (PMID 19543395, 2009).
Atrophy (3 papers, 2025 to 2026). Any weakening or degeneration, especially through lack of use. "Our study further demonstrated mitochondrial atrophy in the mouse brain through ultrastructural analysis, alongside dose-dependent alterations in the levels of GSH, SOD, MDA, CAT, and lipid ROS in HT22 cells." (PMID 41462678, 2025).
autoimmune disease (3 papers, 2020 to 2025). A disorder resulting from loss of function or tissue destruction of an organ or multiple organs, arising from humoral or cellular immune responses of the individual to their own tissue constituents. "On the other hand, CAT-gene mutations have been linked to several autoimmune diseases and can affect gastrointestinal mucosa." (PMID 36555526, 2022).
bladder tumors (3 papers, 2014 to 2022). "Because CAT–Ce6/F-PEI NPs penetrate bladder tumors to decompose endogenous H2O2, they can effectively relieve tumor hypoxia." (PMID 36662059, 2022). "Therefore, compared with hematoporphyrin, intravesical infusion of CAT–Ce6/F–PEI NPs can significantly improve the photodynamic treatment effect and reduce systemic toxicity of orthotopic bladder tumors." (PMID 36662059, 2022). "Interestingly, the in vitro study showed that the highly metastatic (253J BV cell line) bladder tumour cells were characterised by significantly lower CAT activity than nonmetastatic (253J cell line) bladder tumour cells." (PMID 33923108, 2021).
cardiac arrest (3 papers, 2021 to 2023). Cessation of breathing and/or cardiac function. "It has been reported that hypothermia significantly increases the immunoreactivities of superoxide dismutase, catalase, and glutathione peroxidase in the anterior horn of the lumbar spinal cord following cardiac arrest." (PMID 36766758, 2023). "Further investigations and experiments are required to elucidate the role of catalase during post-cardiac arrest syndrome and to evaluate the effects of antioxidant therapy after cardiac arrest." (PMID 34501367, 2021). "Also, the therapeutic administration of DATS decreases brain inflammation and malondialdehyde levels and preserves the activity of the antioxidant enzymes superoxide dismutase (SOD) and catalase (CAT) in cardiac arrest models." (PMID 38136245, 2023). "We hypothesized that the antioxidant enzyme catalase may attenuate these pathophysiological processes after cardiac arrest." (PMID 34501367, 2021). "Because 12 to 72 h after cardiac arrest injury, pathways are still active and aggressive treatment on OHCA patients is typically instituted, we determined catalase 48 h after OHCA." (PMID 34501367, 2021).
colorectal adenocarcinoma (3 papers, 2014 to 2025). The most common type of colorectal carcinoma. "Treatment with NAC, SOD or CAT reduced p,p′-DDE-induced cell proliferation, which indicated that oxidative stress plays important role in p,p′-DDE-induced colorectal adenocarcinoma cell proliferation." (PMID 25386960, 2014). "In this study, we found elevated ROS production, lower GSH content, SOD and CAT activities in p,p′-DDE-treated colorectal adenocarcinoma cells." (PMID 25386960, 2014). "This fraction showed significant antioxidant activity in human normal colon epithelial cells and colorectal adenocarcinoma cells, as measured by the DPPH and FRAP assays, the activation of SOD and CAT enzymes, and the reduction in MDA levels after oxidative stress induction." (PMID 41462669, 2025).
delirium (3 papers, 2021 to 2023). A disorder characterized by confusion; inattentiveness; disorientation; illusions; hallucinations; agitation; and in some instances autonomic nervous system overactivity. "Alternatively, hippocampal levels of superoxide dismutase (SOD), glutathione peroxidase (GSH-Px), and catalase (CAT), species involved in the oxidative stress process, are decreased during delirium." (PMID 34526093, 2021).
dermatophytosis (3 papers, 2020 to 2024). A common fungal infection of the stratum corneum of the skin, hair, or nails by a dermatophyte. "A negative correlation of MDA with the antioxidants β-carotene, SOD, and catalase was noticed in dermatophytosis-affected dogs." (PMID 36087151, 2022). "The results of our study are in agreement with the report of Beighet al., in which decreased catalase and GSH in dogs suffering from dermatophytosis was reported." (PMID 33297315, 2020).
dry eye (3 papers, 2018 to 2024). "In dry-eye syndrome, the expression of antioxidant enzymes, such as superoxide dismutase, catalase, and glutathione peroxidase, is much lower than in controls, and correlates with the severity of dry-eye symptoms." (PMID 29795004, 2018).
E. coli infection (3 papers, 2019 to 2025). "In this study, after E. coli infection, the activities of antioxidases, including GSH-Px, SOD, and CAT, all significantly increased in DIO-E." (PMID 32104715, 2020). "Following E. coli infection, the contents of MDA and GSH, and the activities of GSH-Px, CAT and SOD significantly increased in the liver of both the lean- and DIO-E." (PMID 31085802, 2019). "After E. coli infection, moreover, the contents of MDA, and the activities of GSH and CAT were markedly higher in the lean-E." (PMID 31085802, 2019). "Furthermore, the activities of GSH-Px, SOD, CAT, and GCL in the endometrial tissues significantly decreased after E. coli infection, as did the T-AOC." (PMID 41413615, 2025).
Ehrlich tumor (3 papers, 2019 to 2023). "The administration of CISP to the mice groups bearing ESC considerably decreased the activities of endogenous antioxidants in kidney tissues (SOD, GSH, and CAT) when compared to the mice in the Ehrlich tumor groups and the control group." (PMID 35268707, 2022). "Additionally, combined treatment of nanocomposite with low dose exposure of gamma radiation was reported to induce cancer cell damage by increasing MDA while decreasing GSH, CAT, and SOD in Ehrlich tumor tissue." (PMID 36905557, 2023).
enterocolitis (3 papers, 2024 to 2025). An inflammatory process affecting the small intestine and colon. "Moreover, we detected the decreased levels of PRDX2, HSPA1B, and catalase, suggesting a diminished antioxidative capacity in NEC, which was consistent with previous studies on necrotizing colitis or enterocolitis." (PMID 39562369, 2025).
Erythema (3 papers, 2010 to 2024). Redness of the skin, caused by hyperemia of the capillaries in the lower layers of the skin. "In the catalase gel group, 3 adverse events consisted of application site reactions (itching in 1 case, burning upon application in 1 and itching and erythema in 1) and 1 adverse event consisted of abdominal pain." (PMID 21747844, 2011).
gingivitis (3 papers, 2014 to 2022). A disorder involving inflammation of the gums; may affect surrounding and supporting structures of the teeth. "The examination of CAT in the saliva of our subjects showed a significantly lower mean value in the group of subjects with gingivitis, which indicates impaired antioxidant protection of the inflamed gingiva." (PMID 34204920, 2021). "This study showed lower values of salivary TAC and the activity of antioxidant enzyme CAT in children and young teenagers with gingivitis, while the GPX was not significantly different." (PMID 34204920, 2021). "In the group of subjects without gingivitis, there is a statistically significant positive correlation only between CAT and GPX activities." (PMID 34204920, 2021). "Therefore, the primary aim of this study was to examine the antioxidant activity of saliva by determining the TAC value and activity of antioxidant enzymes—CAT and GPX in children and young teenagers without and with gingivitis." (PMID 34204920, 2021).
Huntington disease (3 papers, 2016 to 2021). Huntington disease (HD) is a rare neurodegenerative disorder of the central nervous system characterized by unwanted choreatic movements, behavioral and psychiatric disturbances and dementia. "CBG treatment also prevented 3‐NP‐induced neuronal loss, recovered catalase, SOD and GSH, compared with control, and down‐regulating genes that were directly associated with Huntington's disease including sgkl, Cd44, and normalized levels of huntingtin‐associated protein‐1." (PMID 32608035, 2020).
hyperandrogenism (3 papers, 2018 to 2022). Excessive secretion of androgens from the adrenal glands or gonads. "Administration of IMODs significantly reduced lipid peroxidation (a marker of oxidative stress) and increased superoxide dismutase, catalase and glutathione peroxidase (markers of antioxidant potential) levels in hyperandrogenism-induced PCOS." (PMID 32903374, 2020). "MDA, CAT, SOD, and GPx activity were insignificantly lower in comparison to that in the PCOS patients without hyperandrogenism." (PMID 35207512, 2022).
immunotoxicity (3 papers, 2015 to 2025). "For instance, it induces oxidative stress and immunotoxicity, as evidenced by changes in catalase (CAT) and glutathione peroxidase (GPX) activity in mouse livers." (PMID 40559927, 2025).
infective endocarditis (3 papers, 2016 to 2024). Infective endocarditis (IE) is an infection of the inner lining of the heart chambers (endocardium) and valves. "Gemella is a catalase-negative, facultative anaerobic, Gram-positive coccus that is commensal in humans but can become opportunistic and cause severe infectious diseases, such as infective endocarditis." (PMID 37887239, 2023).
laryngeal squamous cell carcinoma (3 papers, 2021 to 2025). A squamous cell carcinoma that arises from the larynx. "In contrast to these proliferative responses in breast epithelial cells, 2.1-fold overexpression of tRNA-iMet-CAT in a laryngeal squamous cell carcinoma cell line suppressed proliferation in favour of apoptosis." (PMID 37509247, 2023).
leprosy (3 papers, 2014 to 2022). Leprosy is a chronic infectious disease affecting primarily the skin and peripheral nervous system. "In summary, our data showed that the treatment with MDT in leprosy patients led to a decrease in enzymatic antioxidant systems as CAT, alongside an increase in GSH, as well as a rise in MetHb levels and Heinz bodies' formations." (PMID 24465659, 2014). "In addition, CAT activity was significantly reduced in MDT-treated leprosy patients, while GSH content was increased in these patients." (PMID 24465659, 2014). "Recently, we showed that the treatment with MDT in leprosy patients also led to a significant decrease in CAT activity in leprosy patients, but did not alter the SOD activity compared to untreated patients." (PMID 26284371, 2015).
lipid metabolic disorders (3 papers, 2023 to 2025). "Elevated pro-inflammatory cytokines such as TNF-α and IL-6 have been linked to lipid metabolic disorders, while oxidative stress biomarkers including GSH, CAT, SOD, and MDA are widely recognized indicators of redox homeostasis." (PMID 41304686, 2025).
lymph node metastasis (3 papers, 2019 to 2024). "Particular attention should be paid to CAT for which AUC in the presence of lymph node metastasis was 0.7450 with cut-off value >61.61 nmol H2O2/min/100 mg protein, 65.00% sensitivity and 66.67% specificity." (PMID 31652642, 2019). "Catalase and malondialdehyde can be potential non-invasive biomarkers indicating tumour invasion depth or presence of lymph node metastasis." (PMID 31652642, 2019). "Moreover, we assume that catalase and malondialdehyde—a product of lipid peroxidation—may be potential non-invasive biomarkers differentiating tumour invasion depth or indicating the occurrence of lymph node metastasis." (PMID 31652642, 2019). "The authors stated that blood catalase (CAT) and MDA could be used in CRC diagnostics or as indicators of tumor invasion depth and the presence of lymph node metastasis." (PMID 37107276, 2023).
metastatic tumor (3 papers, 2010 to 2020). "Both in vitro and in vivo findings were reversed with the addition of catalase suggesting that the effect of P-AscH− on metastatic disease is mediated by hydrogen peroxide." (PMID 33077776, 2020). "In another study detoxification of hydrogen peroxide by administration of catalase resulted in a decrease in the MMP activity and cell proliferation in metastatic tumor cells." (PMID 21190578, 2010).
methemoglobinemia (3 papers, 2015 to 2025). An inherited or acquired condition characterized by abnormally increased levels of methemoglobin in the blood. "Decreased catalase activity during acute intestinal inflammation increases intestinal nitrites, leading to oxidative stress and methemoglobinemia." (PMID 40217910, 2025). "At such high concentrations the activity of many enzymes including erythrocytic catalase are likely to be inhibited to a considerable degree thus increasing oxidative stress and methemoglobinemia." (PMID 33508993, 2021).
myelofibrosis (3 papers, 2014 to 2023). A partial or complete replacement of the bone marrow stroma by fibrous tissue. "In our previous work, increased CAT activity was observed in primary myelofibrosis, as the final stage of MPN development." (PMID 35204748, 2022). "Thus, most recently ROS accumulation in JAK2V617F-positive cells has been shown to be associated with a significant decrease in gene expression of CAT - both in a mouse model and in CD34+ cells from PV and myelofibrosis patients." (PMID 25397683, 2014). "Interestingly, the CAT gene was highly significantly downregulated in our patients with ET and PV but not in myelofibrosis." (PMID 25397683, 2014).
Osteopenia (3 papers, 2019 to 2025). Osteopenia is a term to define bone density that is not normal but also not as low as osteoporosis. "Catalase’s capacity to avert osteopenia in mice with ovariectomies highlights the significance of antioxidants for bone health." (PMID 37836554, 2023).
Peptic ulcer (3 papers, 2020 to 2025). The term peptic ulcer refers to acid peptic injury of the digestive tract, resulting in mucosal break reaching the submucosa. "Malvidin efficiently modulated CAT activity in models of peptic ulcer prevention and repair, highlighting the importance of this pathway in the pharmacological activity of anthocyanidins." (PMID 41226784, 2025). "Topiramate pretreatment also reduced the contents of tissue malonaldehyde, enhanced glutathione levels and increased the activity of superoxide dismutase, catalase and glutathione peroxidase in gastric mucosa of rats subjected to indomethacin-induced peptic ulcers." (PMID 38137423, 2023).
postmenopausal osteoporosis (3 papers, 2015 to 2024). Metabolic disorder associated with fractures of the femoral neck, vertebrae, and distal forearm. "The direct interactions of rutin, beta-sitosterol, quercetin, norisoboldine, and hyperoside with key disease-related proteins such as TGFB1, TNF, IL1B, IL6, and CAT suggested that these compounds may modulate critical pathways involved in the pathology of postmenopausal osteoporosis." (PMID 39596387, 2024). "Oxidative stress and inflammation in postmenopausal osteoporosis has been related to the activation of NADPH oxidase and/or decreased synthesis of SOD, CAT, and GSH levels." (PMID 37998727, 2023). "Women with postmenopausal osteoporosis have significantly lower SOD, GPX, CAT activity and higher levels of lipid peroxidation end-product MDA, and the antioxidant enzymes levels are significantly associated with BMD values of the femoral neck, lumbar spine, and total hip。." (PMID 26186010, 2015).
Primary hypothyroidism (3 papers, 2018 to 2025). A type of hypothyroidism that results from a defect in the thyroid gland. "Furthermore, improvement of oxidative stress and enhancement of CAT activity followed by levothyroxine in patients with primary hypothyroidism have been illustrated." (PMID 37144592, 2023). "Furthermore, current results indicated that levothyroxine replacement improved oxidative status in patients with primary hypothyroidism, based on significantly decreased concentrations of MDA and increased CAT activity." (PMID 40256603, 2025). "In the present clinical study, our primary finding is that levothyroxine replacement could improve oxidative status in patients with primary hypothyroidism, indexed by significantly decreased levels of MDA and increased CAT activity after the treatment." (PMID 30467493, 2018).
reflux esophagitis (3 papers, 2022 to 2025). "As a result of this experiment, it was confirmed that SC treatment activated the PPARγ/RXR pathway and increased the expression of antioxidant enzymes such as SOD-1 and catalase in reflux esophagitis." (PMID 35027935, 2022). "In a rat model of reflux esophagitis (RE), Flos Lonicerae (LF) decreased esophageal and gastric mucosal lesions, lipid peroxidation, and collagen accumulation, and enhanced antioxidant indicators such as SOD, CAT, and GSH just like α-tocopherol." (PMID 40292509, 2025).
relapsing-remitting multiple sclerosis (3 papers, 2020 to 2024). The most common clinical variant of multiple sclerosis, characterized by recurrent acute exacerbations of neurologic dysfunction followed by partial or complete recovery. "In this work, the catalytic properties of IgGs with superoxide dismutase activity and catalase activity were studied for the first time in patients with relapsing remitting MS (RRMS) and secondary progressive MS (SPMS)." (PMID 32089782, 2020). "The objective of this study was to investigate the potential correlation of markers of oxidative stress (GSH, catalase) in certain phases of relapsing-remitting multiple sclerosis (RRMS), and to additionally correlate them with the number of demyelinating T2/FLAIR lesions." (PMID 38623459, 2024). "Another study reported about impaired antioxidant enzymes in terms of high activity of catalase and decreased activity of MnSOD in peripheral blood mononuclear cells (PBMCs) from patients with relapsing-remitting multiple sclerosis (RRMS) compared to healthy controls." (PMID 32802267, 2020).